MIR3591 (microRNA 3591)
Synonyms: hsa-mir-3591; hsa-mir-122b
Gene: MicroRNA gene on chromosome 18 (58,451,080 to 58,451,152, reverse strand). Ensembl gene ENSG00000207778.
Gene Ontology:
Biological process: miRNA-mediated post-transcriptional gene silencing
Cellular component: RISC complex